SMIM10L2B-AS1 (SMIM10L2B antisense RNA 1)
Synonyms: ENST00000453528
Gene: Protein-coding gene on chromosome X (135,059,685 to 135,123,952, forward strand). Ensembl gene ENSG00000228372.
Homologues: Orthologues: mouse 1600025M17Rik (37% identical).